STAT2 (signal transducer and activator of transcription 2)
Diseases named in the same sentence as STAT2 in open-access papers (continued):
Sharing a sentence is not in itself a finding about the gene and the disease.
lung carcinoma (7 papers, 2016 to 2023). "The levels of STAT1 and STAT2 mRNAs mirrored the kinetic trajectories observed for other IFN Hallmark genes in the osimertinib-treated lung cancer cell lines but were especially marked in H1650 cells." (PMID 34001994, 2021). "To investigate the role of STAT2 in resistance to cisplatin, we employed three lung cancer cell lines with different expression levels of STAT2: low in A549 cells and high in H196 and Calu-1 cells." (PMID 37036972, 2023). "This function of STAT2 is dependent on its phosphorylation on T404, a high level of which is seen in about 25% of human lung cancer specimens." (PMID 37036972, 2023). "STAT2 has been reported to provide a dominant benefit for proliferation of lung cancer cells." (PMID 36744245, 2023). "The phosphorylation of STAT2 on T404 inhibits the DNA damage response that is induced by exposure of lung cancer cells to cisplatin and may correlate with the infiltration of fewer CD8+ T cells in lung cancers." (PMID 37036972, 2023). "In addition, five of the genes that we identified in this study, CPEB4, DUSP6, NF1, RNF4, and STAT2, were previously proposed as prognostic markers for NSCLC, whereas changes in the expression of MCM4 and WEE1 were associated with lung cancer development." (PMID 27418131, 2016). "Together with STAT2 and p65, IRF9 enhances lung cancer cell growth and, in pancreatitis, promotes proliferation and migration." (PMID 33430083, 2021). "On analyzing data from The Cancer Genome Atlas (TCGA), we found expression levels of IRF9, STAT1, and STAT2 in patients with lung cancer, and IRF9 expression levels were positively correlated with those of STAT1 and STAT2." (PMID 33430083, 2021). "The protein levels of PDL1, IRF1, IRF7, STAT1, STAT2, IFNAR1, eIF2α, and ATF4 in the normal and tumor tissues of 27 subjects with lung cancer were determined by Western blot." (PMID 30305853, 2018). "For every unit increase in the relative expression of STAT2 and RNF4 genes, the odds of having lung cancer dropped by 74% and 84%, respectively." (PMID 27418131, 2016). "The regulation of PDL1 expression in lung cancer may depend on factors other than STAT1 and STAT2 such as NF-κB." (PMID 30305853, 2018). "Similarly, to our findings in patients with lung cancer, the status of STAT2 did not influence survival in these patients." (PMID 33430083, 2021). "The effects of IFN signaling pathway on the PD1/PDL1 axis may not depend on STAT1 or STAT2 in lung cancer." (PMID 30305853, 2018). "The PDL1 expression in lung cancer may be independent of STAT1 and STAT2." (PMID 30305853, 2018).
prostate carcinoma (7 papers, 2011 to 2025). A carcinoma that arises from epithelial cells of the prostate gland. "The data acquired in STAT2‐deficient PC‐3 cells almost completely recapitulated the antitumor phenotypes elicited by TRIM66 knockdown, which implicated the important role of STAT2 in mediating the oncogenic activities of TRIM66 in prostate cancer cells." (PMID 31981447, 2020). "Notably, despite the uncovered TRIM66–STAT2–IL‐2 prostate cancer, the molecular mechanisms underlying TRIM66‐mediated STAT2 regulation were still obscure, which warrants further investigations." (PMID 31981447, 2020). "Our study highlights the importance of the TRIM66–signal transducer and activator of transcription 2–interleukin‐2 signaling axis in the tumor biology of prostate cancer." (PMID 31981447, 2020). "In a study of patients with prostate cancer, 1,25(OH)D was found to suppress many JAK-STAT signal components, including JAK1, STAT1, STAT2 and STAT3, which is consistent with our study." (PMID 32158346, 2020).
psoriasis (7 papers, 2015 to 2024). An autoimmune condition characterized by red, well-delineated plaques with silvery scales that are usually on the extensor surfaces and scalp. "This variant is highly linked with three psoriasis risk SNPs (rs2066807, rs2066808, and rs2066819; r2 = 0.9523, 0.9388, and 0.9517, respectively) located within the STAT2 gene region." (PMID 31969149, 2020). "Taken together, our study sheds light on STAT2 expression and activation in psoriasis and the underlying molecular mechanism involved." (PMID 28472186, 2017). "In order to study if the observed increase in STAT2 expression was specific to psoriasis or simply due to increased inflammation in the skin we also investigated the STAT2 expression in the inflammatory skin disease atopic dermatitis." (PMID 28472186, 2017). "We here present three essential and novel findings, adding new knowledge to the role of STAT2 in the pathogenesis of psoriasis." (PMID 28472186, 2017). "Our data suggest that STAT2 plays a role in the psoriasis pathogenesis by regulating the expression of CXCL11 and CCL5, and thereby attracting IFNγ-producing immune cells to the skin." (PMID 28472186, 2017). "It is therefore possible that STAT2 plays an important role in the migration of immune cells in psoriasis." (PMID 28472186, 2017). "The aim of the present study was therefore to characterize the role of the STAT2 signaling pathway in the pathogenesis of psoriasis." (PMID 28472186, 2017). "The present study aimed to characterize the role of STAT2 in psoriasis." (PMID 28472186, 2017). "It is therefore tempting to speculate that STAT2 plays a role in the pathogenesis of psoriasis by specifically recruiting Th1 cells to the inflammatory site through its regulation of CXCL11 and CCL5." (PMID 28472186, 2017). "Together, these data suggest that STAT2 may play a role in the pathogenesis of psoriasis." (PMID 28472186, 2017). "Moreover, it offers evidence that STAT2 may be a new target for modulating Th1 cell migration in psoriasis." (PMID 28472186, 2017). "However, the role of STAT2 in the pathogenesis of psoriasis is unknown." (PMID 28472186, 2017). "Together, these data indicate that STAT2 upregulation and activation in psoriatic skin is not simply due to inflammation in the skin, but seems to be more specific to psoriasis." (PMID 28472186, 2017). "Interestingly, it was found that the signal transducer and activator of transcription 2 (STAT2) and caspase 3 could be used as a biomarker of psoriasis, because its advanced expression was distinguished as an obvious feature of psoriasis." (PMID 39595528, 2024). "Interestingly, when examining STAT2 in the inflammatory skin disease atopic dermatitis, no increase in STAT2 activation/phosphorylation was detected, suggesting that STAT2 activation is specific to psoriasis and not just a consequence of skin inflammation in general." (PMID 28472186, 2017).
dengue (6 papers, 2012 to 2024). "Dengue virus infection results in loss of STAT2 expression, while West Nile virus infection results in failed JAK activation in an attempt to evade JAK/STAT-mediated immunity." (PMID 32152180, 2020). "For instance, STAT2 was reported to mediate STAT1-independent protection against dengue virus infection in mice that were deficient in STAT1 through the formation of non-ISGF3 complexes that involved STAT2 homodimers, and did not require STAT1." (PMID 26897526, 2016). "Furthermore, when STAT2-deficient MEFs were reconstituted with hSTAT2, dengue replication was unaffected by IFNα/β treatment, but it was inhibited in MEFs expressing mSTAT2." (PMID 22590678, 2012). "Despite the different conditions in vivo, with shifting cell populations and multiple interacting stimuli, 57 of these genes, including canonical ISGs such as ISG15, ISG20, OAS2, ISI27, STAT1 and STAT2, had consistently elevated transcript levels in dengue patients compared to healthy controls." (PMID 23285306, 2012). "Thus, if chikungunya virus interferes with STAT1 nuclear transport and dengue virus blocks STAT2 phosphorylation, inhibiting both STAT1 and STAT2 during chikungunya/dengue coinfection may enhance replication of both viruses." (PMID 30668574, 2019).
measles (6 papers, 2015 to 2025). A highly contagious viral infection caused by the measles virus. "In the cases of RNA viruses, including influenza A, measles, and coronavirus disease, downregulation of genes such as Ddx58, Il1b, Stat1, Stat2, Oas3, Oas2, Oas1a, Oas1g contributes to increased susceptibility to infections." (PMID 40206211, 2025). "Two patients with homozygous variants within STAT2 were found to have significantly decreased phosphorylated serine at serine 637 of DMNL1, with impaired fission in the context of receiving measles, mumps, and rubella vaccination." (PMID 33426505, 2020).
neuroblastoma (6 papers, 2013 to 2023). Neuroblastoma (NB) is the most common solid, extracranial childhood tumor. "In neuroblastoma, it forms a positive feedback loop with miR-653-5p and STAT2 (signal transducer and activator of transcription 2), which sustains an aggressive phenotype of malignant cells." (PMID 32318335, 2020). "The SNHG7-miR-653-5p-STAT2 feedback loop has been disclosed in regulating neuroblastoma progression." (PMID 32228518, 2020). "In neuroblastoma, miR-653-5p targets STAT2 to regulate neuroblastoma cell proliferation and invasion." (PMID 31889959, 2019). "Moreover, in neuroblastoma (z score = 3.22, p = 0.0013), endometrial carcinoma (z score = 2.49, p = 0.0127), and triple negative breast cancer (z score = 2.05, p = 0.04), higher CTL levels all suggested more favorable survival outcomes when STAT2 had relatively low expression." (PMID 36968603, 2023).
cervical carcinoma (5 papers, 2010 to 2023). A carcinoma arising from either the exocervical squamous epithelium or the endocervical glandular epithelium. "The role of STAT2 in cervical cancer is poorly studied, a higher expression of STAT2 has been observed in adenocarcinoma samples compared to normal tissue." (PMID 37372319, 2023). "The effect of V protein variants on components of the interferon-stimulated gene factor 3 (ISGF3), STAT1 and STAT2 proteins were experimentally tested in cervical carcinoma cell lines." (PMID 20937132, 2010). "Therefore, they suggested that the increased expression of STAT2 begins in premalignant dysplasia and remains in cervical cancer." (PMID 33076315, 2020). "However, the role of STAT2 in cervical cancer remains poorly understood and further analysis is needed to determine whether its activation in cervical cancer cells could be a good or a bad prognostic factor." (PMID 33076315, 2020). "In a study on cervical cancer, the importance of IFN-inducible activation of STAT1 and STAT2 was demonstrated through the use of STAT1 and STAT2 knockout human HeLa cells, yet the STAT3 knockout did not have any effect on ISGs." (PMID 33329603, 2020).
colon carcinoma (5 papers, 2007 to 2025). "In this study, we found that higher levels of STAT2 in colon cancer were linked to poorer patient survival." (PMID 41440237, 2025). "To determine whether this function depends on type I IFN receptor (IFNAR1) signaling, we generated IFNAR1 knockout (IFNAR1 KO) colon carcinoma cells and compared their growth with parental and STAT2-deficient (STAT2 KO) tumor cells." (PMID 41440237, 2025). "Together, these results indicate that, like the human model, loss of STAT2 or IFNAR1 disrupts IFN-I-dependent transcription, although the downstream signaling consequences differ between the two genes in murine colon carcinoma cells." (PMID 41440237, 2025). "Here, we show that high STAT2 mRNA expression in colon cancer tumors correlates with reduced overall survival in patients." (PMID 41440237, 2025). "Our findings demonstrate that STAT2 functions as a tumor-promoting factor in colon cancer, acting independently of canonical IFNAR1-mediated type I interferon signaling." (PMID 41440237, 2025). "In this study, we provide experimental evidence that STAT2 plays a tumor-promoting role in colon cancer that is distinct from the canonical, tumor-suppressive effects of IFNAR1-mediated IFN-I signaling." (PMID 41440237, 2025). "Other studies have shown that STAT2 promotes chemoresistance driven by increased STAT2 expression, an important observation that warrants further investigation, given that high STAT2 levels in colon cancer correlate with reduced overall survival." (PMID 41440237, 2025). "Our findings challenge the conventional view of STAT2 as solely a mediator of IFN-I-dependent antitumor immunity and instead support a context-dependent function for STAT2 as a tumor promoter in colon cancer." (PMID 41440237, 2025). "To confirm the physical binding, we further obtained STAT2 ChIP-seq profiles of colon cancer cells for validation." (PMID 35946310, 2022). "Profiles from Xena database showed that STAT2 was widely expressed in multiple cancer types, including colon cancers." (PMID 35946310, 2022). "To determine whether the differential effects of STAT2 and IFNAR1 deletion observed in human cells were conserved in a murine context, we evaluated STAT2- and IFNAR1-deficient mouse MC38 colon carcinoma cell lines." (PMID 41440237, 2025). "Moreover, overexpression of STAT2 in colon cancer cells accelerated tumor growth in vivo, further supporting a tumor-promoting role for STAT2." (PMID 41440237, 2025). "Targeting STAT2 or its downstream pathways may, therefore, represent a novel therapeutic strategy for mitigating colon cancer progression." (PMID 41440237, 2025). "Moreover, the HPA database indicated that in the tumour microenvironment of colon cancers, STAT2 could be detected in multiple cell types, including cancer cells." (PMID 35946310, 2022). "Therefore, we hypothesized that the interaction of STAT2 and PD-L1 might influence colon cancers in an immune-related way." (PMID 35946310, 2022). "Together, these results demonstrate that, despite their shared involvement in IFN-I signaling, STAT2 and IFNAR1 exert opposing effects on colon cancer cell proliferation and tumor progression." (PMID 41440237, 2025). "In colon cancer, oncogenic K-ras inhibits the expression of IFN-responsive genes through inhibition of STAT1 and STAT2 expression." (PMID 18506145, 2008). "Based on the LinkedOmics database, we found that the STAT2 expression was significantly lower in no-MSI colon cancers." (PMID 35946310, 2022). "In addition, the LinkedOmics database demonstrated that the STAT2 expression was significantly lower in patients with MSS (non-MSI) colon cancer compared to that in patients with MSI-H colon cancer." (PMID 35946310, 2022).
lung adenocarcinoma (5 papers, 2018 to 2025). A carcinoma that arises from the lung and is characterized by the presence of malignant glandular epithelial cells. "Consistent with our new findings on the ability of STAT2 to inhibit STING-dependent signaling, there is a significant association between high levels of STAT2 in tumors and shorter overall survival in patients with lung adenocarcinomas." (PMID 37036972, 2023). "Third, STAT2-dependent inhibition of STING promoted chemotherapy resistance and tumor progression in a study reporting a significant association between high STAT2 tumor levels and shorter overall survival in patients with lung adenocarcinomas." (PMID 38001683, 2023). "The mRNA and protein levels of STAT2 were significantly higher than those in sensitive lung adenocarcinoma cells." (PMID 40713600, 2025). "In contrast, when murine cell lines CMT64/61 (C57BL/6 lung adenocarcinoma) and NIH/3T3 (murine fibroblast, deficient in some steps of IFN signaling) were infected with HMPV, we saw increased total and phosphorylated STAT1 and STAT2." (PMID 32635475, 2020). "Based on our finding that STAT2 preferentially inhibits the induction of IRF3-dependent genes, we propose that the IKKi-induced T404 phosphorylation of STAT2 mediates tumor progression in lung adenocarcinoma by inhibiting the tumor-suppressive function of the cGAS–STING pathway." (PMID 37036972, 2023). "Although STAT1 and STAT2 activate IRF1, the protein level of IRF1 was not correlated with that of STAT2 in all the tissues and had a significant correlation with that of STAT1 only in the normal tissue of lung adenocarcinoma." (PMID 30305853, 2018).
pancreatic cancer (5 papers, 2020 to 2025). "Another study demonstrated that in pancreatic cancer, ZBED2 represses differentiation and dampens STAT2-mediated inflammatory response through IRES binding competition with IRF1." (PMID 36944729, 2023). "In pancreatic cancer, HER2 also stimulates the JAK pathway through the activation of Src kinase and Src-mediated STAT2 nuclear translocation in the pancreatic cancer model." (PMID 36291900, 2022).
bladder cancer (4 papers, 2011 to 2025). "We have also identified the activation of ERK1/2, p38MAPK, JNK, JAK1, JAK2, JAK3, Stat1, Stat2, and Stat3 in bladder cancer cells." (PMID 22962576, 2012). "Our results from bladder cancer cells indicate that IL-20 induced activation of ERK1/2 and Jak1, Jak2, Jak3, Stat1, Stat2, and Stat5." (PMID 22962576, 2012). "In addition, in bladder cancer cell J82 with down-regulated expression of CHAF1A, some down-regulated expression of several genes related to cell growth and proliferation were found, including STAT2, STAT6, AKT2, IRS1 and SOX4." (PMID 37575547, 2023).
encephalitis (4 papers, 2019 to 2025). An acute inflammatory process affecting the brain parenchyma. "Notably, STAT2-humanized mice developed more severe encephalitis than C57BL/6J or IFN receptor-deficient mice, suggesting JEV employs a STAT2 degradation mechanism similar to that of DENV and ZIKV." (PMID 40855992, 2025). "Japanese encephalitis virus (JEV), a leading cause of viral encephalitis in Asia and the Western Pacific, is regulated by type I interferon (IFN) signaling pathway, in which STAT2 is critical." (PMID 40855992, 2025).
Flavivirus Infections (4 papers, 2019 to 2024). Infections with viruses of the genus FLAVIVIRUS, family FLAVIVIRIDAE. "Moreover, USP18 competes with NS5-mediated STAT2 degradation, a major mechanism for establishment of flavivirus infection." (PMID 38384473, 2024). "This study also showed that knockout of PDLIM2 resulted in less efficient IFN-α-mediated STAT2 degradation; however, STAT2 degradation during flavivirus infection was not investigated in PDLIM2–/– cells." (PMID 31652496, 2019).
leukemia (4 papers, 2020 to 2022). A malignant (clonal) hematologic disorder, involving hematopoietic stem cells and characterized by the presence of primitive or atypical myeloid or lymphoid cells in the bone marrow and the blood. "Loss of STAT2 expression in Jurkat leukemia cells results in resistance to type I interferon-induced apoptosis." (PMID 35207629, 2022). "Loss of STAT2 in leukemia and osteosarcoma cells leads to resistance of interferon-α-induced apoptosis." (PMID 35207629, 2022). "Studies have also indicated that HCMV IE1 protein inhibits the transcription of ISGs by sequestering its binding of promyelocytic leukemia (PML) and STAT2, thus decreasing IFN responses while increasing IFN-β tolerance in the virus." (PMID 34305856, 2021).